GSTP1 (glutathione S-transferase pi 1)
Diseases named in the same sentence as GSTP1 in open-access papers (continued):
Sharing a sentence is not in itself a finding about the gene and the disease.
Pca (2 papers, 2013 to 2022). "Aberrant promoter hypermethylation and concomitant gene silencing have been observed at several genes in PCa, such as GSTP1, RASSF1, APC, CCND2, and PITX2." (PMID 36551580, 2022). "Various reports demonstrated that hypermethylation events at genes with prognostic implications in PCa tissue (e.g., GSTP1, APC, and PTGS2) are also detectable in plasma, serum, or urine samples." (PMID 36551580, 2022). "Deletions in GSTP1, CDKN1B, and ARID1A have been shown to be associated with the risk of hereditary PCa and metastasis formation." (PMID 36551580, 2022). "In a case/control study whose cohorts has now been included in the present enlarged populations, we previously found that polymorphisms in oxidative-stress control-related GSTP1, PON1-192, PON-1 55 and CYP17 genes were associated with the risk of PCa." (PMID 24040147, 2013). "GSTP1, APC, RARB, and PITX2 are among the most extensively studied prognostic 5-mC biomarkers in Pca, and numerous reports emphasize their value as prognostic markers when analyzed in resected prostate tissues." (PMID 36551580, 2022). "For instance, a urinary 4-gene 5-mC panel (i.e., GSTP1, APC, CRIP3, and HOXD8) was found to predict disease progression in patients with Gleason 6 PCa under active surveillance." (PMID 36551580, 2022). "The combined analysis of GSTP1, RASSF1, and APC showed superiority relative to the histological assessment of biopsy specimens, detecting PCa in 62 and 68% of histologically negative biopsies in two independent, large-scale studies (498 and 350 biopsies analyzed, respectively)." (PMID 36551580, 2022).
preeclampsia (2 papers, 2011 to 2025). Preeclampsia is a hypertensive disorder of pregnancy that is characterized by new-onset hypertension with proteinuria presenting after 20 weeks of gestation, and depending on mild or severe forms may initially present with severe headache, visual disturbances, and hyperreflexia. "To this end, we have utilized the transmission disequilibrium test or TDT developed as a test for linkage between a complex disease, such as preeclampsia and a genetic marker, such as the polymorphic alleles of the GSTP1, eNOS, and LPL genes." (PMID 20836743, 2011). "The paternal and fetal polymorphism of the GSTP1 gene was found to be associated with a high risk for preeclampsia." (PMID 20836743, 2011). "This new approach has been used so far in a single study to address the effect of the paternal contribution, by studying the GSTP1 gene polymorphism in a cohort of 113 preeclampsia trios in the Dutch population." (PMID 20836743, 2011). "It is of interest that homozygosity for the Val105 polymorphism was associated with severe preeclampsia because of the production of a GSTP1 enzyme with reduced detoxifying capacity." (PMID 20836743, 2011). "It has also been speculated that the GSTP1 variant contributes to preeclampsia phenotype despite the fact that the frequency of the Ile105/Val105 and Val105/Val105 genotypes was not significantly different between the preeclampsia and the control group." (PMID 20836743, 2011). "The results revealed that five out of the six serum biomarkers of kidney injury were elevated in the preeclampsia group compared to the control group (calbindin 1, clusterin, glutathione transferase pi (GSTP1), monocyte chemotactic protein 1 (MCP-1), and kidney injury molecule type 1 (KIM-1))." (PMID 40649927, 2025). "Glutathione S-transferase P1 (GSTP1), endothelial nitric oxide synthase (eNOS), and lipoprotein lipase (LPL) constitute three major detoxification enzymes that have been studied in pregnancy, as putative predisposing factors to preeclampsia." (PMID 20836743, 2011). "The GSTP1 polymorphism with its variant Val105 allele is not sufficient to clearly confer an increased risk for preeclampsia, neither the eNOS polymorphism with the variant 298Asp allele, nor the LPL gene polymorphism with the -93G variant allele." (PMID 20836743, 2011). "We hypothesized that these gene polymorphisms might constitute a basis for the triggering events leading to preeclampsia, by affecting the activity of biotransformation enzymes (GSTP1 and eNOS) in detoxifying processes and/or the endothelial function (LPL)." (PMID 20836743, 2011). "For the GSTP1 polymorphism, the frequency of the variant Val105 allele interestingly was found to be higher in mothers and fathers of normal pregnancies compared to the preeclampsia group, a finding nonconsistent with previous data." (PMID 20836743, 2011). "However, the transmission rates of the parental alleles to neonates studied by the transmission disequilibrium test, disclosed no increased rate of transmission to preeclampsia children for the variant alleles of Val105 GSTP1, 298Asp eNOS, and -93G LPL." (PMID 20836743, 2011). "We next studied the distribution of the frequencies of GSTP1, eNOS, and LPL genotypes in the subgroups of the mothers, fathers, and children of the preeclampsia and normal control groups." (PMID 20836743, 2011). "Additionally, the serum concentrations of calbindin 1, clusterin, GSTP1, and KIM-1 were significantly higher in both early-onset and late-onset preeclampsia compared to the control group." (PMID 40649927, 2025).
radiation pneumonitis (2 papers, 2021 to 2025). Inflammation of the lung due to harmful effects of ionizing or non-ionizing radiation. "A well-known polymorphism, GSTP1 Ile105Val, is associated with reduced enzymatic efficiency, which may explain susceptibility to radiation pneumonitis and possibly skin toxicity in other settings." (PMID 40507362, 2025). "Furthermore, clinical data finds that patients with GSTP1 SNP 105Ile/Val had significantly higher risk of radiation pneumonitis (RP) of grade ≥ 2 (P = 0.001), which strongly indicates that GSTP1 is closely associated with the occurrence and development of RILI." (PMID 34238333, 2021).
scleroderma (2 papers, 2006 to 2021). Scleroderma is a rare autoimmune connective tissue disorder characterized by abnormal hardening of the skin and, sometimes, other organs. "Recently, Tourkina and colleagues demonstrated a deficiency in GSTP1 in scleroderma lung fibroblasts." (PMID 17044913, 2006).
seminoma (2 papers, 1993 to 2024). A radiosensitive malignant germ cell tumor found in the testis (especially undescended), and extragonadal sites (anterior mediastinum and pineal gland). "In immunohistochemical staining, non-seminomatous germ cell tumours, which are more refractory than seminomas to anti-cancer chemotherapy, frequently expressed Pgp and GSTP1-1." (PMID 8100442, 1993). "Western blot analysis demonstrated lower amount of GSTP1-1 in seminoma than in teratoma." (PMID 8100442, 1993). "CtDNA hypermethylation at APC, GSTP1, PTGS2, p14, p16, and RASSF1A was investigated to detect seminomas and nonseminomas, with detected methylation patterns found to be similar between seminoma and nonseminomas." (PMID 38927984, 2024).
transitional cell carcinoma (2 papers, 2010 to 2022). A malignant neoplasm arising from the transitional epithelium, usually affecting the urinary bladder, ureter, or renal pelvis. "Transitional cell carcinoma (TCC) of urinary bladder belongs to glutathione S-transferase P1 (GSTP1) overexpressing tumors." (PMID 21637416, 2010). "GSTP1 is overexpressed in many tumors, including transitional cell carcinoma (TCC) of urinary bladder, where its activity and expression correlate with tumor stage and grade." (PMID 21637416, 2010).
viral infection (2 papers, 2019 to 2021). "Some proximal genes targeted by these 6 REs (FSCN1, GSTP1, JAM3, CHRNA6, NFAT5, and PRRC2A) are related to immune response, viral infection, and/or HCC based on ontological analysis." (PMID 31639042, 2019).
xeroderma pigmentosum group D (2 papers, 2008 to 2022). Any xeroderma pigmentosum in which the cause of the disease is a mutation in the ERCC2 gene. "We studied the usefulness of the excision repair cross-complementing 1 (ERCC1), xeroderma pigmentosum group D (XPD), XRCC1 and GSTP1 polymorphisms as predictors of clinical outcome in these patients." (PMID 18797464, 2008).
acute hepatitis B (1 paper, 2023). "Consequently, GSTP1 may be a possible predictive biomarker of acute liver failure linked to acute hepatitis B.159The methylation of GSTP1 has a significant impact on liver illnesses and may be used to treat those diseases." (PMID 37901797, 2023).
Adenocarcinoma of cervix (1 paper, 2015). "Adenocarcinoma of cervix was significantly higher in the patients having AG+GG genotype of GSTP1 (P = 0.02)." (PMID 26571237, 2015).
agranulocytosis (1 paper, 2018). "GSTP1 is highly expressed in neutrophils, where it may protect against AQ-induced agranulocytosis." (PMID 29720942, 2018).
allergic asthma (1 paper, 2019). A asthma with a basis in a pathological type I hypersensitivity reaction. "Also, association of GSTP1 slow genotype with allergic asthma or IgE- mediated reactions have earlier been suggested." (PMID 31649932, 2019).
alopecia (1 paper, 2019). Hair loss usually from the scalp. "Grades III–IV vomiting, nausea, and alopecia could be partly explained by the presence of specific ERCC1/2, MDR1, GSTP1, and BLMH genotypes (p < 0.05)." (PMID 30914949, 2019). "Grades III–IV vomiting, nausea and alopecia could also be partly explained by the presence of specific ERCC1/2, MDR1, GSTP1, and BLMH genotypes." (PMID 30914949, 2019).
atopic asthma (1 paper, 2022). An asthma that is characterized by symptoms that are triggered by an allergic reaction caused by inhaled allergens such as dust mite allergen, pet dander, pollen and mold. "A case control study in Turkey found that subjects with GSTP1 homozygous Val/Val genotypes had a 3.55 fold increased risk of atopic asthma in adulthood (95%CI 1.10, 12.56) compared to those with homozygous Ile/Ile genotypes." (PMID 36250015, 2022).
bronchiolitis (1 paper, 2014). Inflammation of the bronchioles characterized by swelling of the bronchioles and mucus accumulation. "Analysis of the three genotypes showed that, infants with the GG genotype of GSTP1 (rs1695) had a significantly increased risk of LRTIs, especially bronchiolitis, during the first year of life (aOR 22.04, 95% CI: 4.79–101.47; aOR 14.61, 95% CI: 3.23–66.11, respectively)." (PMID 25263840, 2014). "Exposure to high levels of perinatal anxiety increased the risk of bronchiolitis in the first year of life (adjusted odds ratio [aOR], 1.30; 95% confidence interval [CI]: 1.00–1.80), in particular among children with the AG + GG genotype of GSTP1 or the GSTT1 null genotype (aOR 3.36 and 2.79)." (PMID 25263840, 2014).
carotid atherosclerosis (1 paper, 2010). A thickening and loss of elasticity of the walls of carotid arteries that occur with formation of atherosclerotic plaques.
cataract (1 paper, 2021). Partial or complete opacity of the crystalline lens of one or both eyes that decreases visual acuity and eventually results in blindness. "GSTP1 levels were reduced in the human AH samples from the POAG combined with cataract group, based on the results of ELISA and proteomic profiling." (PMID 33599104, 2021).
chronic rhinosinusitis (1 paper, 2019). Chronic form of sinusitis. "There is statistical correlation between the polymorphisms of the GSTT1, GSTM1, and GSTP1 genes and the genetic tendency of chronic rhinosinusitis with or without nasal polyps in Germany." (PMID 30617052, 2019).
clear cell renal cell carcinoma (1 paper, 2022). "Interestingly, there is a similar case showing a synergistic effect from the alleles of GSTM1-null, GSTT1-present, GSTA1/T (low activity), and GSTP1/G (low activity) on promoting risk for clear cell renal cell carcinoma." (PMID 35572141, 2022).
cognitive decline (1 paper, 2025). "In contrast, Rapid Decline showed increased β-amyloid (bA), glial and inflammatory markers (CD44, PLXNB1), and stress- and mitochondrial-related proteins (GSTP1, AK4, HSPB2, FBXO2, IGFBP5), which have been associated with neurodegeneration and cognitive decline in AD." (PMID 40799531, 2025).
cryptogenic cirrhosis (1 paper, 2020). "GSTP1, a member of the GST superfamily, impacts hepatic conditions in patients with cryptogenic cirrhosis because of its expression in the biliary epithelium." (PMID 33291080, 2020).
dementia (1 paper, 2023). Loss of intellectual abilities interfering with an individual's social and occupational functions. "Observed associations of polymorphisms in CAT, GSTP1, NFE2L2 and KEAP1 with dementia support the importance of antioxidative mechanisms in AD." (PMID 36829875, 2023). "Among antioxidative genes, CAT, GSTP1, NOS1, NFE2L2, and KEAP1 were associated with dementia or AD." (PMID 36829875, 2023).
diabetic neuropathy (1 paper, 2015). A chronic, pathological complication associated with diabetes mellitus, where nerve damages are incurred due to diabetic microvascular injury involving small blood vessels that supply these nerves, resulting in peripheral and/or autonomic nerve dysfunction. "We investigated the relation between polymorphism in genes related to oxidative stress such as GSTM1, GSTT1, and GSTP1 and the presence of T2DM and diabetic neuropathy (DN)." (PMID 26435566, 2015).
dysplasia (1 paper, 2016). A usually neoplastic transformation of the cell, associated with altered architectural tissue patterns. "Likewise, inverse correlation between GSTP1 expression and Barrett's esophageal metaplasia-dysplasia-adenocarcinoma sequence was demonstrated." (PMID 27206673, 2016).
endotoxemia (1 paper, 2011). "Both GSTA1-1 and GSTP1-1 levels, respectively, increased during experimental endotoxemia (n = 30, P < 0.0001)." (PMID 21211004, 2011).
esophagitis (1 paper, 2022). An acute or chronic inflammatory disease affecting the esophageal wall. "Furthermore, MMP-9 expression is inversely correlated with protein levels of the phase II detoxification glutathione-s-transferase pi (GSTP1), with increased levels of GSTP1 in normal patients and those with esophagitis." (PMID 35267943, 2022).
glomerulosclerosis (1 paper, 2023). A hardening of the kidney glomerulus caused by scarring of the blood vessels. "Gstp1 also plays an important role in detoxification with reduced glutathione, which was also upregulated in glomerulosclerosis." (PMID 38077419, 2023).
Glucose intolerance (1 paper, 2021). Glucose intolerance (GI) can be defined as dysglycemia that comprises both prediabetes and diabetes. "In a recent study, a Gstp1 polymorphism was associated with increased glucose intolerance and greater androgen production in non-obese women with polycystic ovary syndrome." (PMID 34041258, 2021).
Hand-foot syndrome (1 paper, 2020). "Hand-foot syndrome and hematopoietic toxicity could not be demonstrated a statistically significant association with GSTP1 genotype in our study." (PMID 33280607, 2020).
hay fever (1 paper, 2016). "GSTP1 polymorphisms did not modify the association between TRAP exposure during the first year of life and current hay fever at any time point." (PMID 27043549, 2016).
Hematuria (1 paper, 2015). The presence of blood in the urine. "In addition, patients with the GSTP1 rs1695 AA genotype had an increased risk of irritative voiding symptoms; while patients with the GSTO1 rs4925 CC genotype had a decreased risk of hematuria." (PMID 26354850, 2015). "Interestingly, a significant association was found between the GSTP1 rs1695 and GSTO1 rs4925 genotypes and the prevalence of hematuria and irritative voiding symptoms in the epirubicin-treated group." (PMID 26354850, 2015).
hemorrhagic cystitis (1 paper, 2017). Inflammation of the bladder resulting in bloody urine. "Among other GST genes investigated, GSTP1 313GG correlated with acute graft versus host disease grade 1-4 (p=0.01) and GSTM1 non-null genotype was associated with hemorrhagic cystitis (p=0.003)." (PMID 29207608, 2017).
Hodgkins lymphoma (1 paper, 2006). A heterogeneous group of malignant lymphoid neoplasms of B-cell origin characterized histologically by the presence of Hodgkin and Reed-Sternberg (HRS) cells in the vast majority of cases. "In a study of patients with Hodgkin's lymphoma, the low activity GSTP1 genotype was associated with better survival." (PMID 16848913, 2006).
hypospadias (1 paper, 2023). Hypospadias is the displacement of the urethral meatus on the ventrum of the penis. "While these non-synonymous homozygous ADGRA2, EGF, F13A1, IRF6, and GSTP1 genes mutation might encode mutant proteins, they do not provide a prediction of the phenotype, but may contribute to more accurate assessments of the orofacial clefts or hypospadias." (PMID 37238140, 2023).
kidney injury (1 paper, 2025). Trauma to the kidney. "Calbindin 1, clusterin, GSTP1, KIM-1, and MCP-1 concentrations in maternal plasma could be used in the monitoring of kidney injury in preeclamptic women; however, there is a need to perform longitudinal studies." (PMID 40649927, 2025).
lactic acidosis (1 paper, 2023). Metabolic acidosis characterized by the accumulation of lactate in the body. "Our findings imply that GSTP1 plays key roles in regulating metabolism subject to modulation upon sensing the tumor metabolic microenvironment lactic acidosis." (PMID 37491277, 2023). "We ectopically expressed Flag-tagged GSTP1 in three cell lines (MCF-7, Bcap37, and 293 T) and used cell lysates mixed with M2 beads to immuno-precipitate (IP) tagged GSTP1 with or without lactic acidosis." (PMID 37491277, 2023). "Previous paper reported that GSTP1 promoted the S-glutathionylation of SRC under TNF-α stimulation, but is not found under lactic acidosis in our paper." (PMID 37491277, 2023).
leukopenia (1 paper, 2019). "Following adjustment for other potential risk factors, it was shown that GSTP1 variants only were associated with increased risks of leukopenia." (PMID 30987408, 2019). "The authors found, in the univariate analysis, that GSTM1 wildtype genotype had a relationship with leukopenia and flue like symptoms, while GSTP1 variant was strongly associated with leukopenia." (PMID 30987408, 2019).
Lewy body dementia (1 paper, 2017). A progressive form of dementia characterized by the presence of protein deposits called Lewy bodies in the midbrain and cerebral cortex, and loss of cholinergic and dopaminergic neurons. "The abundance of SYNPO was lower whereas GSTP1 and PLP1 level were higher in Lewy body dementias and its clinical subtypes." (PMID 28800743, 2017). "On the other hand, VIM, PLP1 and GSTP1 failed to display significant alteration (p > 0.05) between control and either subtypes of Lewy body dementias." (PMID 28800743, 2017).
liver dysfunction (1 paper, 2025). "GSTP1, an antioxidant enzyme that neutralizes reactive oxygen species (ROS), may contribute to the accumulation of oxidative stress when downregulated, thereby triggering apoptosis and liver dysfunction." (PMID 40880651, 2025).
lupus nephritis (1 paper, 2016). Glomerulonephritis in the context of systemic lupus erythematosus. "In conclusion, our study showed that polymorphims of the GSTM1 and GSTP1 could impact remission and ADRs in lupus nephritis treated with CYC." (PMID 27002825, 2016).
male infertility (1 paper, 2024). The inability of the male to effect fertilization of an ovum after a specified period of unprotected intercourse. "Concerning the link between GST polymorphisms and the urogenital system, some research shown that variations in GSTM1, GSTT1, and GSTP1 are linked to male infertility." (PMID 39063019, 2024).